LGALS3 (galectin 3)
Diseases named in the same sentence as LGALS3 in open-access papers (continued):
Sharing a sentence is not in itself a finding about the gene and the disease.
tumor (continued). "The galectin-3 protein is also highly expressed in tumor cells and N-acetyllactosamine is a well-established ligand of this receptor." (PMID 34073528, 2021). "It has been demonstrated that IFNγ entrapment by galectin-3 in the tumor extracellular matrix prevents the creation of such a chemokine gradient required to attract T cells towards the tumor." (PMID 34572756, 2021). "Among the last ones, we can mention that inhibition of galectin-1 or galectin-3 both potentiates tumor cell sensitivity to several types of chemotherapies (involving different molecular mechanisms) in a panoply of different cancers." (PMID 34572756, 2021). "Tumor galectin-3 is an additional potent regulator of lymphocyte effector properties at the tumor site." (PMID 34572756, 2021). "Recently, another novel dual-targeting 68Ga-NODAGA-LacN-E[c(RGDfK)]2Glycopeptide has also been developed for PET imaging of cancer patients, which can diagnose integrin αvβ3 and galectin-3 expression in tumor and tumor endothelial cells." (PMID 34445532, 2021). "We suppose that the synthetized, novel 68Ga-NODAGA-LacN-E[c(RGDfK)]2 radiopharmaceutical will be suitable for the detection of αvβ3 integrin and galectin-3 expression in tumor and tumor endothelial cells with PET imaging." (PMID 34073528, 2021). "By including gene-edited tumors and RNA sequencing, this organ-on-chip revealed that platelets and tumors interact through glycoprotein VI (GPVI) and tumor galectin-3 under shear." (PMID 34290095, 2021). "On the other hand, the expression of galectin-3 by the stroma is required to recruit CD4+ CD25+ FOXP3+ Tregs towards immune organs in tumor-harboring mice." (PMID 34572756, 2021). "Risk scores were correlated with tumor stage; BMF was associated with age, gender, grade, and stage; PPP2R5B and LGALS3 were correlated with stage; SQSTM1 was associated with age and gender; while TOP2A was correlated with grade and stage." (PMID 33712023, 2021). "Interaction of TF/MUC1 with galectin-3 also enhances tumor cell–endothelial heterotypic adhesion in circulating tumor cell extravasation." (PMID 34944925, 2021). "Cancer cell proliferation increased in OTME-Chips relative to controls during 40 to 72 hours of extravasated platelets and tumor interaction, and proliferation was found diminished in galectin-3 KO–OTME-Chips." (PMID 34290095, 2021). "This study demonstrated the central role LAG-3 plays in galectin-3-mediated suppression of lymphocyte anti-tumor effector function." (PMID 34572756, 2021). "First, the galectin-3 expression on tumor cells negatively impacts the T lymphocyte numbers in lymph nodes." (PMID 34572756, 2021). "Since the type of tumor in this study was different from the previously reported tumor, it was considered that the results of galectin-3 levels in dogs with neoplasia would be different from previous results." (PMID 34722704, 2021). "Here, the molecules responsible for the cellular adhesion and specific tumor recognition were reported to be EpCAM, N-cadherin and galectin-3, which were present on the cancer cell surface." (PMID 34070233, 2021). "These galectin-3-mediated effects are local (inside the tumor) since the functional unresponsiveness of TILs contrasts with the functional properties of blood T cells." (PMID 34572756, 2021). "Our previous studies have shown that circulating PNA mimics the actions of endogenous galactoside-binding protein galectin-3 by interaction with tumour cell-associated MUC1 and promotes circulating tumour cell metastatic spreading." (PMID 34223877, 2021). "Among them, galectin-3 (Gal-3) is involved in cell adhesion, proliferation, migration, apoptosis, tumour progression, inflammation and innate and adaptative immune system modulation." (PMID 33906678, 2021). "Galectin-3–induced αvβ3 integrin clustering drives KRAS addiction in tumor cells, and galectin-3 inhibition represents an actionable target to treat KRAS G12D-bearing cancers." (PMID 34131655, 2021).
tumor (continued). "Nanoliposome encapsulating photosensitizer Chlorin e6 and Galectin-3 (Gal-3) inhibitor enhanced the ability of Natural Killer (NK) cells to recognize tumor cells after PDT." (PMID 34051801, 2021). "Galectin-3 is another member of this lectin family with a significant impact on the anti-tumor lymphocyte activation occurring in the draining lymph nodes." (PMID 34572756, 2021). "The interaction between the tumor cells and the matrix protein elastin is mediated by elastin-binding proteins (EBPs), S-Gal, and Galectin-3 through the expression and release of elastases." (PMID 34827210, 2021). "Given the involvement of galectin-3 in tumor angiogenesis, these results suggested a central role for this lectin during GBM progression." (PMID 35008740, 2021). "Galectin-3 is a beta-galactoside-binding animal lectin related to various mechanisms in tumor development and is believed to play a role in the malignant transformation of thyroid cells." (PMID 34833464, 2021). "Amino-terminally truncated galectin-3 (Gal-3C) has been studied in the therapy of galectin-3-related tumours and seems to be a promising therapeutic target, showing a low toxicity profile." (PMID 35053194, 2021). "Galectin‐3 (gal‐3) is a b‐galactoside binding protein that is involved in several types of pathological tumour progression, such as angiogenesis, cell proliferation and anti‐apoptosis." (PMID 33300633, 2021). "The dysfunctional state of intra-tumor lymphocytes induced by galectin-3 is further supported by their expression of terminal T cell deactivation/exhaustion markers." (PMID 34572756, 2021). "The study aimed to evaluate the relationship between clinical features, tumor behavior, and the expression of galectin-3 and ERα, in a homogenous and retrospective surgical cohort of patients affected by prolactinoma with long-term follow-up." (PMID 34322092, 2021). "Overexpression of galectin-3 cDNA in vitro generates a transformed phenotype; conversely, inhibition of Gal-3 expression has suppressed tumor growth in mice tumor models." (PMID 34203725, 2021). "Along the same lines, LGALS3 protein expression was increased in HCC tumours, compared to adjacent tissue." (PMID 34794390, 2021). "For instance, tumor cells can recognize galectin-3 via their BCR as well as independently of the BCR." (PMID 34944954, 2021). "This is the case with increased expression of galectin-3, a beta-galactoside-binding protein, which inhibits adhesion between tumor cells and with extracellular matrix, and therefore promotes cell mobility and tumor invasiveness." (PMID 34858978, 2021). "Altogether, these data seem to indicate galectin-3 plays a role at the initial steps of tumor antigen presentation." (PMID 34572756, 2021). "LGALS3 (Galectin-3) is mainly involved in cell growth, cell adhesion, cell differentiation, and tumor progression and metastasis owing to its action of binding to glycoproteins." (PMID 33820866, 2021). "Circulating galectin-3 actively promotes metastasis by direct interaction with circulating tumour cells or the vascular endothelium." (PMID 34223877, 2021). "Galectin-3 is a member of the galectin-binding lectin family and is a multifunctional protein with a variety of biological functions, including tumor cell proliferation and invasion and angiogenesis." (PMID 32351643, 2020). "Initial proliferation of resting peripheral blood and tumor-infiltrating Vδ2-expressing γδ T cells was impaired by galectin-3 in a cell-cell-contact dependent manner." (PMID 32695112, 2020). "In cancer, galectin-3 overexpression in the TME is associated with angiogenesis, tumor progression, and immune escape by inducing T cell apoptosis." (PMID 32063906, 2020). "By focusing on the co-culture of tumor cells and γδ T cells, we observed that knockdown of galectin-3 in tumor cells identified these cells as the source of secreted galectin-3." (PMID 32695112, 2020).
tumor (continued). "The expression of β-galactoside-binding protein galectin-3 is regarded as an intrinsic tumor escape mechanism for inhibition of tumor-infiltrating T cell function." (PMID 32695112, 2020). "In contrast, when galectin-3 binds carbohydrates on the surface of tumor cells, it induces apoptosis of these cells and increases the immune response against the tumor cells." (PMID 32033052, 2020). "Two experimental works were published that show the role of galectin 3 in the in vivo spread of the tumor." (PMID 32859099, 2020). "We analyzed also the relationship between EP2 staining and the FIGO stage or the tumor stage in the high galectin-3 subgroup." (PMID 31980713, 2020). "A further two-group analysis between NIBUC and MIBUC also demonstrated the overexpression of DEPs with a tumor-suppressive role, including LGALS3 and VAPA in NIBUC." (PMID 32326232, 2020). "The effects of Galectin-3 on tumour metastasis were investigated in vitro and in vivo, and the underlying biological and molecular mechanisms involved in this process were evaluated." (PMID 32801345, 2020). "In these tumors, low levels of galectin-3 are indicative of a more aggressive and invasive tumor, while normal or even high levels of galectin-3 were associated with less invasive tumors." (PMID 32033052, 2020). "Galectin-3 is a protein with approximate molecular weight of 31 kDa, first recognized in murine immune cells, and thereafter found in a variety of normal and tumor cells." (PMID 32455781, 2020). "Galectin-3 (Gal-3) is an extracellular matrix glycan-binding protein with several immunosuppressive and pro-tumor functions." (PMID 33013832, 2020). "Galectin-3 released by tumor cells or addition of physiological concentrations of recombinant galectin-3 did neither further inhibit the impaired γδ T cell cytotoxicity against PDAC cells nor did it induce cell death of in vitro expanded γδ T cells." (PMID 32695112, 2020). "Both endogenous and secreted LGALS3 were upregulated in HCC tumor tissue and serum samples, which was highly correlated with poor survival." (PMID 32564007, 2020). "LGALS3 is a member of the β-galactosidase-binding lectin family, mediating the proliferation, differentiation, and angiogenesis of tumor cells to promote cancer progression via endogenous and secretion mechanisms." (PMID 32564007, 2020). "Mice with xenografts derived from Galectin-3-overexpressing cells displayed a higher photo flux and tumour weight, which was partially abrogated by β-catenin knockdown." (PMID 32801345, 2020). "Galectin-3, a lately discovered β-galactoside-binding protein expressed on tumor cells, was described as NKp30 inhibitor, restraining NKp30-mediated NK functions and tumor escape elimination by NK cells." (PMID 32612950, 2020). "Its interaction with galectin 1 and galectin 3 leads to tumor cell aggregation and promotes cancer metastasis and T-cell apoptosis in epithelial tissue." (PMID 32367478, 2020). "Galectin-3 is considered to be a metastasis-inducing protein that is expressed by tumor and inflammatory cells." (PMID 33255941, 2020). "Pectins are considered as tumor targeting agents via β-galactose units, which can bind specifically to the galectin-3 adhesive molecule (overexpressed in various types of cancers)." (PMID 32235765, 2020). "Galectin-3, a β-galactoside-binding protein, is known to be involved in multiple roles in cancer development and progression including tumor cell growth, adhesion, angiogenesis, invasion, anti-apoptosis, and metastasis." (PMID 32235765, 2020). "Next, we focused on the relationship between M2BPGi as a tumour promoter and galectin-3 as a representative M2BP-binding protein." (PMID 32624579, 2020). "Altered galectin-3 expression is correlated to the stage of tumor progression in many types of carcinoma, such as colon, thyroid, breast and prostate cancer." (PMID 31980713, 2020).
tumor (continued). "We observed that the large majority of patients (about 90%) with high galectin-3 tumor expression (score 3+) showed an early and dramatic progression of the disease after three cycles of treatments." (PMID 30935099, 2019). "Galectin-3 is localized mainly in tumour cells, macrophages, epithelial cells, fibroblasts, activated T cells." (PMID 31652641, 2019). "In this complex scenario, galectin-1 and galectin-3 deserve consideration for the functional implications they can have on tumor immune response." (PMID 30935099, 2019). "Exogenously added galectin-3 contributed to the migration of many tumor cells mainly through interaction with ECM glycoprotein partners, such as fibronectin, laminin, collagen type IV47." (PMID 30765738, 2019). "The Cav1 MDA-MB-435 pseudopod proteome included galectin-3 supporting a role for local pCav1-galectin-3 signaling to drive invadopod protrusion and tumor cell invasion." (PMID 31803361, 2019). "Expression of galectin-1 and galectin-3 in tumor cells can block apoptosis; when shed in the tumor microenvironment, both galectins induce T cell apoptosis via CD45 and CD7 binding on T cell surface, favoring, indeed, tumor immune escape." (PMID 30935099, 2019). "Cav1 tumor suppressor activity is conditional on expression of galectin-3 and receptor N-glycosylation while pCav1 acts in concert with galectin-3 to promote FA turnover and tumor cell migration and invasion." (PMID 31803361, 2019). "The finding that experimental transfer of cytotoxic T lymphocytes in vivo reduces tumor growth only after galectin-3 inactivation further support the key role of galectin-3 in favoring tumor immune escape." (PMID 30935099, 2019). "The first two ligands bind to and activate NKp30 while the released form of galectin-3 inhibits anti-tumor NKp30 function." (PMID 31736972, 2019). "Galectin-3 is a β-galactoside-binding lectin that has been reported to be a critical immune regulator in the tumor microenvironment." (PMID 31134055, 2019). "In cancer biology galectin-3 is overexpressed in migrating cells during wound healing, and during tumor invasion and metastasis." (PMID 30765738, 2019). "Galectin-3 is a relatively abundant component of the tumor microenvironment, where it has been found to regulate critical aspects of cancer biology, such as metastasis, apoptosis, and immune surveillance." (PMID 31540324, 2019). "Galactopyranosides with aryl-aminopyrimidine moieties at O3 inhibit the tumor and immunity-related galectin-3 with high selectivity over other galectins." (PMID 31303989, 2019). "Soluble galectin-3 derived by tumor shedding, binds specific glycan residues in the tumor microenvironment, forming a complex lattice." (PMID 30935099, 2019). "Immunotherapy targeting the galectin-3 would be better strategy to control tumor growth and invasion." (PMID 29983921, 2018). "Decreased galectin 3 expression relative to that of normal cells or adjacent tissues has also been reported in multiple tumour types." (PMID 29386018, 2018). "Galectin-3 is also expressed in PCa lesions, exerts direct pro-tumor and pro-metastatic functions, and correlates with biochemical recurrence." (PMID 30108594, 2018). "One elegant study demonstrated that tumor-derived galectin-3 captured IFN-γ in tumor matrices and subsequently downregulated IFN-γ-induced chemokine gradients." (PMID 29389859, 2018). "In a tumor environment the interaction of galectin-3 with T cells effector cytokine IFN-γ compromised its protective function, and the effect is extracellular in nature." (PMID 30388704, 2018). "Galectin-3 is a protein involved in cell proliferation, adhesion, differentiation, angiogenesis, and apoptosis in normal and pathologic tissues; recent studies indicate that Galectin-3 plays a role in tumor cell transformation and metastasis." (PMID 30282914, 2018).
tumor (continued). "In the interfollicular zone (IFZ) of tumor-free cervical lymph nodes of oscc patients, the Galectin 3 (Gal3) cell count in T2 oscc was significantly higher than in T1 cases (median 153 cells/mm2 and 69 cells/mm2, respectively, p = 0.040)." (PMID 30115022, 2018). "For example, LAMP1 carries significantly higher levels of PolyLacNAc, and has high affinity ligands for galectin-3 on tumor cell surface." (PMID 29875690, 2018). "Up to now, a growing number of researches have suggested the involvement of galectin-3 in tumor progression and disease outcome." (PMID 30410421, 2018). "In tongue cancer cells, Galectin-3 mediates tumor metastasis and invasion through Wnt/β-catenin signaling pathway and Akt phosphorylation." (PMID 29254179, 2017). "Galectin-3 was believed to modulate the adaptive strategies of cancer cells in stressed tumor microenvironments." (PMID 29254179, 2017). "The adhesion molecules ICAM-1, VCAM-1, E-selectin and galectin-3 as well as the chemokine system CXCL12/CXCR4 have been reported to be involved in the interaction of tumor and endothelial cells." (PMID 29100413, 2017). "Galectin-3 is involved in many biological activities including tumor metastasis and tumor angiogenesis." (PMID 28264434, 2017). "Galectin-3 also plays a pro-inflammatory role and promotes tumor progression by modulating tumor cell survival and metastasis." (PMID 28744198, 2017). "Altogether, these data indicate that both the tumor matrix and the extracellular galectin-3 cooperate to limit the spreading of IFNγ signaling." (PMID 28986561, 2017). "The increased tumor T-cell infiltration driven by anti-galectin-3 antibody was completely abrogated by AMG478 administration without affecting the number of T cells found in the spleens." (PMID 28986561, 2017). "Particularly, patients with high-grade urothelial carcinoma have higher serum levels of galectin-3 than those with low-grade tumours." (PMID 29207682, 2017). "Our data indicate that the tumor ECM has an essential role in the retention of IFNγ by galectin-3, as collagenase D treatment resulted in increased IFNγ availability and CXCL9 gradient formation." (PMID 28986561, 2017). "Galectin-3 plays different roles in the process of tumor growth including cell differentiation, adhesion, migration, invasion, metastasis and angiogenesis." (PMID 29254179, 2017). "Taken together, up-regulation of Galectin-3 contributed to the increased tumor cell migration in response to hypoxic microenvironments." (PMID 29254179, 2017). "We have therefore used an immunocompromised mouse model bearing a human tumor and injected an anti-galectin-3 antibody locally inside the tumor." (PMID 28986561, 2017). "Here the authors show that galectin-3 secreted by tumours binds both glycosylated IFNγ and glycoproteins of the tumour extracellular matrix, thus avoiding IFNγ diffusion and the formation of an IFNγ-induced chemokine gradient required for T cell infiltration." (PMID 28986561, 2017). "We also identified galectin-3 as a tumor-derived factor hampering the generation of tumor-reactive T cells in a MLTC." (PMID 28401257, 2017). "Under normal circumstances, galectin-3 protein can be expressed in many tissues, and research shows that it would overexpress constantly due to the severity of the disease in a variety of tumor tissues." (PMID 28355349, 2017). "Assuming its main functional activities in this context are via TAMs, we propose a dynamic process in which galectin-3 contributes to apoptosis induced in the tumor cell population by antitumor macrophage activity." (PMID 28157210, 2017). "All together, these data indicate that the presence of galectin-3 is a limiting factor for IFNγ-induced CXCL9/10 expression by tumor cells." (PMID 28986561, 2017). "The carbohydrate recognition domain of Galectin-3 (Gal3C) has been reported to be an anti-tumour molecule." (PMID 28701735, 2017).